IL6 (interleukin 6)
Diseases named in the same sentence as IL6 in open-access papers (continued):
Sharing a sentence is not in itself a finding about the gene and the disease.
tumor (continued). "In the tumor microenvironment across various cancer types, IL-6/JAK/STAT3 signaling promotes tumor cell growth, survival, invasiveness, and metastasis, while significantly suppressing the antitumor immune response." (PMID 41596531, 2026). "Pro-inflammatory cytokines such as IL-6 and IL-8 are central drivers of tumor progression, angiogenesis, and epithelial–EMT." (PMID 41497141, 2026). "In contrast, tumor-secreted factors including parathyroid hormone-related protein (PTHrP) and interleukin-6 aberrantly induce uncoupling protein 1 (UCP1) expression and β3-adrenergic signaling, driving lipolysis and energy wasting in CAC." (PMID 41848823, 2026). "After isolating only the malignant tumor cells, we analyzed IL‐6/STAT3 signaling and the resistant and sensitive signatures of TMZ extracted from analyzing Depmap data in four clusters." (PMID 41556041, 2026). "Pro-inflammatory cytokines such as TNF-α, IFN-β, and IL-6 were significantly elevated in tumor tissues and serum compared to those in the PBS group." (PMID 41583068, 2026). "By contrast, 3D-primed ADSCs preserved organoid structure but markedly enhanced tumor cell migration through soluble factors, accompanied by increased IL-6 and TNF-α and reduced IL-10 secretion during co-culture." (PMID 41681933, 2026). "Pro-inflammatory cytokines, including IL-6 and IL-8, are frequently upregulated in dysbiotic states and have been shown to activate NF-κB signaling, a pathway known to enhance tumor cell proliferation, migration, and invasion." (PMID 41486167, 2026). "Monocytes and macrophages, depending on their phenotype, can either enhance anti-tumor immunity or promote tumor growth by regulating cytokines such as IL-6." (PMID 42079657, 2026). "Stratified analyses showed a lower frequency of the IL6 rs1800795 C allele and TNF rs1800629 GA genotype in high-grade and muscle-invasive tumors, suggesting potential associations with reduced tumor aggressiveness." (PMID 42074005, 2026). "The process is further driven by multiple signaling pathways—most notably TGF-β/Smad, Wnt/β-catenin, Notch, and HIF-1α—and modulated by cytokines such as IL-6, IL-8, TNF-α, HGF, and PDGF, frequently secreted by tumor-associated stromal cells." (PMID 41595527, 2026). "In this case, the peripheral blood lymphocyte count decreased, and the interleukin-6 level was markedly elevated, which was thought to reflect T-cell accumulation in the tumor." (PMID 41835784, 2026). "Tumor volume and morphological changes in various organs were observed, and the serum concentrations of IL-6, IL-10, and TNF-α were assessed." (PMID 41901226, 2026). "Cytokines such as interleukin-6 (IL-6), tumor necrosis factor-alpha (TNF-α), IL-1β, and IL-8 are implicated in enhancing tumor growth, immune evasion, and metastasis." (PMID 41497141, 2026). "This review synthesizes evidence on the roles and molecular mechanisms of major myokines-including IL-6, irisin, SPARC, oncostatin M (OSM), and decorin-in exercise-associated modulation of cancer-related inflammation and tumor progression." (PMID 41983081, 2026). "Daily intragastric administration of Pt517 significantly inhibited tumor growth in mice; increased the expression levels of TNF-α, INF-γ, and CD8 in tumor tissues; and decreased the levels of IL-6, IL-10, and TGF-β." (PMID 42121906, 2026). "These M1 macrophages release pro-inflammatory cytokines (TNF-α, IL-1β, IL-6, IL-12) and generate reactive oxygen/nitrogen species to attack tumor cells and recruit lymphocytes." (PMID 41597210, 2026). "IL-17 has been shown to contribute to tumor growth by inducing the production of IL-6, which activates the oncogenic transcription factor STAT3." (PMID 41486167, 2026). "NF-κB and STAT3 pathways crosstalk with enhance the production of pro-inflammatory cytokines like IL-6, which create a tumour permissive microenvironment." (PMID 41476776, 2026).
tumor (continued). "In summary, IL-6, TNF-α, IL-17A, and CXCL8 (IL-8) emerge as the cytokines most strongly linked to promoting anoikis resistance in tumor cells, activating survival pathways like NF-κB, STAT3, and AKT/ERK." (PMID 41596231, 2026). "In its subnetwork, leptin is linked to HIF‐1α, IL‐1β, and IL‐6, suggesting some influence over the control of those drivers' downstream effects such as EMT and tumor invasion." (PMID 41450167, 2026). "Inflammatory factors and damage-associated molecular patterns(DAMPs) activate this pathway, increasing expression of TNF-α, IL-6, and other pro-inflammatory mediators to amplify inflammation and sustain a tumor-promoting environment." (PMID 41601649, 2026). "This positions FOSL1 as an upstream regulator of IL‐6 signaling, which contributes to the persistence of therapy‐resistant tumor populations." (PMID 41556041, 2026). "Within TME, IL-6 is produced by various cell types, including tumor-infiltrating immune cells, stromal cells, and the tumor cells themselves." (PMID 41596531, 2026). "Recent studies have demonstrated that tumor epithelial cells not only increase IL-6 production in adipocytes but also increase IL-6R levels in myocytes and subsequently sIL-6R levels in plasma, which induce myotube wasting and adipocyte lipolysis." (PMID 41526343, 2026). "BALF data obtained during routine clinical care were retrospectively collected for tumor markers (CEA, CYFRA21-1, NSE, ProGRP), cytokines (IL-6, IL-8, TNF-α, IL-10), ctDNA mutation profiles, and immune-cell subpopulations." (PMID 41970393, 2026). "For instance, VNS can suppress the production of key protumorigenic cytokines such as IL‐6, IL‐1β, and TNF‐α—critical drivers of tumor‐associated inflammation—thereby enhancing T cell‐mediated immune responses." (PMID 41583906, 2026). "Though FNG is primarily produced by the liver in response to cytokines like IL‐6 and IL‐1β, our data suggest that tumor‐derived cytokines also contribute to elevated FNG." (PMID 41549214, 2026). "Compared with the MCC + NIR group, because of the positive regulatory effect of antimicrobial peptides on the inflammatory tumour microenvironment, there were also significant differences in the expression levels of IL-6 and IL-1β in the PfCC+NIR group." (PMID 41484054, 2026). "They produce matrix metalloproteinases (MMPs) that degrade extracellular matrix and secrete growth factors and cytokines such as VEGF, FGF, IL-6, and IL-12, promoting angiogenesis, tumor growth, invasion, and metastasis." (PMID 41438574, 2026). "Elevated serum IL-6 has been correlated with tumor burden, immune dysregulation, and poor prognosis, while VEGF levels reflect angiogenic activity within the TME." (PMID 41497141, 2026). "As shown, M1 macrophage markers-including IL-1β, IL-6, iNOS, and TNFα-were significantly increased in THP-1 cells co-cultured with N4BP1-deficient TSCC cells compared to those co-cultured with control tumor cells." (PMID 41513619, 2026). "TLR4 activation in prostate cancer cells promotes tumor progression: LPS stimulation in DU145 cells triggers NF-κB–dependent production of IL-6 and IL-1β, while in PC3 cells it enhances VEGF and TGF-β1 expression." (PMID 41601666, 2026). "The results showed that the tumor volume and weight in the IL-6 group increased significantly, confirming that IL-6 promoted tumor proliferation." (PMID 41602823, 2026). "In tumor tissues, the expression levels of Notch1 and Hes1 were dramatically upregulated in the IL-6 group." (PMID 41602823, 2026). "In myeloid immune cells, particularly macrophages, adrenergic signaling—particularly β‐adrenergic—plays a crucial role in tumor progression by facilitating the secretion of various immunosuppressive molecules such as IL‐6, TGF‐β, VEGF, MMPs, and COX‐2." (PMID 41583906, 2026). "Subsequently, these tumor cells produce IL-6 during the tumor phase, triggering autocrine senescence and leading to invasive growth and malignant development." (PMID 41602167, 2026).
tumor (continued). "Both IL6/IL8 play myriad roles in the tumour microenvironment, regulating processes such as cell growth, survival, angiogenesis, epithelial-mesenchymal transition, and polarisation of infiltrating immune cells." (PMID 41249451, 2026). "The interplay of adrenergic signaling in macrophage recruitment is underscored by NE‐induced IL‐6 production and stromal cell activation, which bolster tumor cell migration and neural invasion." (PMID 41583906, 2026). "IL-6 activates tumor cells to induce the expression of STAT3 target genes, which in turn encode proteins that promote tumor growth (such as cyclin D1) and/or survival (such as BCL-2-like protein 1 (BCL-xL)." (PMID 41596531, 2026). "The TME itself modulates Th17 plasticity, with chemokines such as CCL20, CCL17, and CCL22 recruiting Th17 cells, while tumor-derived cytokines such as IL-1β, IL-6, IL-23, and TGF-β promote their differentiation." (PMID 41486167, 2026). "Activation of STAT3 and upstream cytokines such as IL-6 promotes tumor cell survival, stromal remodeling, and resistance to 5-fluorouracil (5-FU) and oxaliplatin through modulation of EMT, DNA repair pathways, and anti-apoptotic programs." (PMID 41516350, 2026). "In HNSCC, IL-6 has been shown to be markedly elevated in the saliva or blood samples from patients and independently predicts tumour recurrence, poor survival, and tumour metastasis." (PMID 39858048, 2025). "Platelets promote the growth and invasion of tumour cells and the formation of metastatic foci through degranulation and release of proinflammatory cytokines (e.g., interleukin-6) and tumor growth factors (e.g., TGF-β)." (PMID 40227669, 2025). "Tumor co-culture induced further enhancement of M1-associated markers including CD80/CD86, MHC-II and IL-1β/IL-6/TNF-α/IL-12/IFN-γ, while suppressing M2 markers CD163/CD206, indicating tumor-triggered M1 polarization." (PMID 41388305, 2025). "In this trial, the authors aim to reduce the chimeric monoclonal antibody that specifically targets IL-6 molecules in the immunosuppressive tumor environment." (PMID 40523922, 2025). "Elevated stromal TAGLN was associated with lymphatic metastasis and enhanced fibroblast activation and motility, which was mediated in part by NF-κB pathway activation and IL-6 secretion, thereby fostering a pro-inflammatory, tumor-promoting microenvironment." (PMID 40940809, 2025). "(G) Flow cytometry analysis for intracellular phospho-S6 in macrophages from tumors in A. (H) Tumor tissue was lysed and the lysates were collected for detection of IL-6 by ELISA." (PMID 40920087, 2025). "High levels of IL-6 and the soluble IL-6 receptor alpha chain (IL-6Rα) play an important role in suppression of the immune response in tumor progression of non-small cell lung cancer (NSCLC)." (PMID 40963621, 2025). "Researchers found that CAF autophagy upregulates the expression of USP14 in PDAC tumor cells through IL‐6, thereby promoting elevated levels of CD274/PD‐L1 and inducing immunotherapy resistance in PDAC." (PMID 41164803, 2025). "STAT3 activation can occur independently of IL-6 targeting, as it lies downstream to other cytokines including IL-10, IL-22, and IL-27, which are broadly pro-tumor in nature and found in abundance in KM-LUAD." (PMID 40356899, 2025). "Combining abemaciclib with IL-6 pathway inhibitors like bazedoxifene enhances anti-tumor efficacy, offering a potentially promising therapeutic approach." (PMID 41148817, 2025). "When CD8+ T cells from peripheral blood and tumor tissues of NSCLC patients were stimulated with IL-6, the expression level of exhaustion markers, especially PD1, was further elevated." (PMID 40040705, 2025). "Polymorphisms in genes encoding cytokines (IL6, TNF, and IL10) and HLA molecules influence the liver’s immunological tolerance and tumor surveillance capacity." (PMID 40869967, 2025). "Conversely, supplementing tumor cell-derived CM with exogenous IL-6 significantly increased CT26 cell survival under L-OHP treatment." (PMID 40718440, 2025).
tumor (continued). "Adiponectin exerts anti-tumor activity by suppressing the secretion of pro-inflammatory cytokines, e.g., IL-6 and TNF-α, lessening the chronic inflammation related to obesity or the anti-inflammatory effect." (PMID 40227577, 2025). "Serum IL-6 levels at Cycle 2 Day 1 were lower in patients whose tumours had disease control by CT scan evaluation." (PMID 39820336, 2025). "In gastric cancer, specific microbial configurations correlate with activation of tumor-promoting pathways such as NF-κB and IL-6/STAT3, which enhance tumor growth, angiogenesis, and immune evasion." (PMID 41189901, 2025). "Chronic inflammation contributes to local tumor growth through sustained cytokine signaling (IL-6, TNF-α), fibroblast activation, and angiogenesis, but does not necessarily drive metastasis." (PMID 41374930, 2025). "In this context, IL-6 trans-signaling stimulates tumor cell proliferation and inhibits apoptosis through activation of gp130, JAKs, and STAT3 in tumor cells." (PMID 40944094, 2025). "This clinical pattern suggests structural fragility induced by tumour infiltration, mediated by cytokines such as IL-6 and NF-κB activation mechanisms." (PMID 41230305, 2025). "Elevated systemic CRP levels activate pro-tumorigenic signaling cascades, including NF-κB and MAPK pathways, inducing tumor cells to secrete proinflammatory cytokines, such as IL-6 and TNF-α." (PMID 40563367, 2025). "As high levels of IL6 have been reported in the microenvironment of several tumor types including breast carcinomas with a poor prognosis, current studies focus on the use of such molecules as JAK-STAT pathway modulators in cancer treatment." (PMID 41463071, 2025). "TNBC cell lines treated with CoCl2 in order to mimic the hypoxic tumoral environment displayed an amplified IL-6/IL-6 receptor level responsible for sustained MAO-A inhibition which in turn promoted tumor angiogenesis and invasion." (PMID 39714760, 2025). "Chemotherapeutic agents, such as cisplatin, induce IL-6 expression in endothelial cells, which in turn enhances VM through tumor–endothelial cell crosstalk." (PMID 41400702, 2025). "IL-6, a well-characterized pro-inflammatory cytokine, plays an important role in tumor progression and metastasis by supporting chronic inflammation and immune evasion." (PMID 41154628, 2025). "Systemic IL‐6 overexpression in tumour‐bearing mice can accelerate muscle wasting, and high circulating IL‐6 levels coincided with suppressed muscle mTORC1 and upregulated AMPK signalling." (PMID 40931444, 2025). "The IL-6 not only stimulates the proliferation of Tfh tumor cells but also imparts pro-survival and anti-apoptotic signals to adjacent plasma cells, thereby promoting the clonal expansion of plasma cells." (PMID 41357603, 2025). "Studies in colorectal cancer have demonstrated that transfection with miR-29b mimics can target the 3’UTR of TLR1/7/8, inhibit their expression, reduce IL-6 secretion, and reverse Treg-mediated immunosuppression, indicating its tumor-suppressive role." (PMID 41488647, 2025). "STAT3 subsequently transduces the signal, resulting in IL-6 and IL-10 production, therefore amplifying this chronic pro-inflammatory loop and inducing tumor growth." (PMID 41463071, 2025). "Preclinical studies using anti-IL-6 or anti-IL-6 receptor (IL-6R) antibodies in tumor-bearing mice demonstrate attenuation of muscle atrophy, adipose tissue loss, and systemic inflammation." (PMID 40704145, 2025). "However, the long-term implications of these changes, particularly in relation to cancer recurrence, warrant further investigation, as sustained elevations in IL-6 have been associated with chronic inflammation and may promote tumor progression in other contexts." (PMID 40608178, 2025). "IL-6 emerged as a particularly important cytokine, significantly overexpressed in both the plasma and tumor tissue of patients, especially those with advanced-stage or TNBC." (PMID 40612845, 2025).
tumor (continued). "Blocking IL-6 not only induces immunogenic cell death (ICD) in tumor cells but also reprograms TAMs toward the M1 phenotype, effectively overcoming ICI resistance while minimizing immune-related adverse events." (PMID 40380196, 2025). "Concurrently, ELISA analysis indicated that tumor cells with higher MSN expression exhibited increased levels of secreted IL-6, while those with low MSN expression had reduced levels." (PMID 40696387, 2025). "Elevated IL-6 expression driven by XBP1s promotes tumor cell proliferation through activation of the STAT3 signaling pathway." (PMID 40278350, 2025). "Evidence suggests that tumor cells release cytokines (e.g., IL-6) to activate astrocytes via JAK/STAT and GFAP signaling." (PMID 40149331, 2025). "Further investigations reveal that IL‐6 produced by bone marrow‐derived cells not only boosts the growth of tumor‐initiating cells but also helps protect normal and precancerous intestinal epithelial cells (IECs) from cell death." (PMID 40548181, 2025). "The levels of IL1A and IL6 were higher in patients with advanced stages than in those with tumor stage 1." (PMID 40860188, 2025). "Interleukin-6(IL-6), produced by the tumor or surrounding cells, stimulates the liver to produce acute-phase response proteins (such as CRP and fibrinogen), both in the fasted and fed states." (PMID 40004975, 2025). "IL-6, in the tumor microenvironment of HNSCC, plays a role in mediating EMT and increasing the metastatic potential of tumor cells via the signaling pathway of JAK/STAT3/Snail." (PMID 39941858, 2025). "WC reflects visceral fat, which is metabolically more active than subcutaneous fat and secretes pro-tumorigenic cytokines including leptin, TNF-α, and IL-6, all of which promote a pro-metastatic tumor microenvironment." (PMID 41139205, 2025). "Elevated IL-6 levels are associated with poor prognosis, tumor progression, and resistance to therapy, as IL-6 can promote an immunosuppressive microenvironment that supports tumor growth." (PMID 40486614, 2025). "Pro-inflammatory cytokines such as IL-6, IL-8, IL-16, and IL-32 were included due to their involvement in tumor growth, angiogenesis, and chemoresistance." (PMID 40652770, 2025). "This activation leads to IRF3 phosphorylation and production of type I interferons (e.g., IFN-β) and inflammatory cytokines (e.g., CXCL10, IL-6), enhancing the tumor’s immune profile." (PMID 39949780, 2025). "IL6 is known to promote STAT3 activation, which has been widely implicated in cancer-induced immune tolerance and tumor progression." (PMID 41514627, 2025). "NF-kB activation upregulates cytokines and growth factors in gene expression, promoting proliferation, tumor cell survival, and angiogenesis (through IL-6, IL-8, TNF-α, and COX-2 upregulation)." (PMID 40723879, 2025). "The multi-functional cytokine interleukin-6 (IL-6) regulates immune system function, promotes blood cell production, and promotes tumour growth." (PMID 41153383, 2025). "A combination of this therapy has been shown to decrease IL-6 serum levels and resulted in tumor regression in xenograft mouse models." (PMID 40227644, 2025). "As potent pro-angiogenic mediators, IL-6 and IL-8 facilitate tumor–endothelial cell crosstalk, thereby enhancing neovascularization." (PMID 40868199, 2025). "In vivo, IL-6 blockade reduces angiogenesis and recruitment of immunosuppressive myeloid-derived suppressor cells (MDSCs), slowing tumor regrowth after SBRT." (PMID 40725389, 2025). "Concurrently, lactate reshapes the tumor immune landscape through dual-phase macrophage polarization - suppressing M1 phagocytic activity via IL-6/ARG1/CCL5 downregulation while enhancing M2 pro-tumorigenic functions through CCL18 induction." (PMID 40843350, 2025).